VDAC1 (voltage dependent anion channel 1)
Diseases named in the same sentence as VDAC1 in open-access papers (continued):
Sharing a sentence is not in itself a finding about the gene and the disease.
mesothelioma (4 papers, 2022 to 2024). A usually malignant and aggressive neoplasm of the mesothelium which is often associated with exposure to asbestos. "Silencing VDAC1 is used for the treatment of mesothelioma and some other tumors but this approach is inapplicable to OSCC because VDAC1′s expression is decreased already." (PMID 37046443, 2023). "To date, the only positive results were achieved when VDAC1 silencing was applied to the treatment of mesothelioma." (PMID 37046443, 2023). "As expected, si-m\hVDAC1-B silenced VDAC1 expression in both human mesothelioma H226 and in mouse mesothelioma AB1 cancer cell lines, as analyzed by immunoblotting." (PMID 35883451, 2022). "In this study, we used siRNA-mediated silencing of VDAC1 expression in mesothelioma cell lines of mouse and human origin and in mouse models using these same mesothelioma cell lines." (PMID 35883451, 2022). "Because VDAC1 overexpression in mesothelioma indicates its importance for cancer development and survival, its silencing by means of RNA interference is expected to inhibit cancer cell proliferation and, therefore, tumor growth." (PMID 35883451, 2022). "We demonstrate that VDAC1 is overexpressed in mesothelioma patients; its levels increase with disease stage and are associated with low survival rates." (PMID 35883451, 2022). "The effects of silencing VDAC1 expression using si-m/hVDAC1-B on mesothelioma tumors were analyzed on established subcutaneous models of mesothelioma using human cells, NCI-H226, and an allogeneic mouse model using AB1 mouse cells." (PMID 35883451, 2022). "This study demonstrates the potential of silencing the expression of the mitochondrial gatekeeper VDAC1 by specific siRNA to treat mesothelioma; si-m/hVDAC1-B can identify both human and mouse VDAC1 and is modified in several nucleotides to increase stability and decrease immunogenicity." (PMID 35883451, 2022). "Thus, VDAC1 silencing can serve as a novel therapeutic approach to treat mesothelioma." (PMID 35883451, 2022). "Thus, silencing VDAC1 is a potential therapeutic approach to treating mesothelioma." (PMID 35883451, 2022). "Thus, our study shows that VDAC1 depletion represents a trigger for reprogramming malignant cancer cells into a post-mitotic state and probably into terminally differentiated cells, and that this might be a promising therapeutic approach for mesothelioma and various cancers." (PMID 35883451, 2022). "Thus, as reported for other cancers, deletion of VDAC1 resulted in metabolism reprogramming in mesothelioma, while targeting global cell metabolism, rather than an individual enzyme or pathway." (PMID 35883451, 2022).
Obesity (4 papers, 2020 to 2025). Accumulation of substantial excess body fat. "In conclusion, our findings demonstrated that AO inhibited the opening of the mPTP and reduced the release of mtDNA from overwhelmed BAT cells in obesity by decreasing CypD acetylation, upregulating mitophagy and suppressing oligomerization of VDAC1." (PMID 40133913, 2025). "The prevention of diet-induced obesity in rats inhibits the expression of the voltage-dependent anion channel 1 (VDAC1) protein, which is a component of voltage-dependent channels in the outer mitochondrial membrane where hydrophilic molecules diffuse." (PMID 39857594, 2024).
atherosclerosis (3 papers, 2025 to 2026). A disease characterized by the build-up of fatty material and calcium deposition in the arterial wall resulting in partial or complete occlusion of the arterial lumen. "Aberrant activity of specific transporters—such as MCU complex-induced Ca2+ overload triggering mPTP opening in ischemia–reperfusion injury, VDAC1 oligomerization facilitating ROS leakage in atherosclerosis, and TRPC3/6-mediated Ca2+ influx promoting fibrosis—orchestrates hallmark features of CVDs." (PMID 40943400, 2025).
Cerebral ischemia (3 papers, 2018 to 2021). Restriction of arterial blood supply to the brain associated with insufficient oxygenation to support the metabolic requirements of the tissue. "Our results showed that brain ischemia and reperfusion caused the downregulation VDAC1 and VDAC3, whereas VDAC2 was least affected after global ischemia." (PMID 30305621, 2018). "Immunohistochemical and western blot analyses showed overexpression of VDAC1 following cerebral ischemia/reperfusion injury in rats." (PMID 32581711, 2020).
Cholangiocellular Carcinoma (3 papers, 2019 to 2022). "Conversely, in cholangiocellular carcinoma, the low expression of VDAC1 correlated with higher cancer stage classification, lymph node involvement, and reduced survival." (PMID 33680287, 2021).
chronic lymphocytic leukemia (3 papers, 2017 to 2022). "VDAC1 was also found to be overexpressed in peripheral blood mononuclear cells (PBMCs) from chronic lymphocytic leukemia (CLL) patients, as compared to PBMCs from healthy donors." (PMID 28824871, 2017).
colon adenocarcinoma (3 papers, 2022 to 2025). "In this context, the oncogenic potential of a somatic missense mutation p.E73D in VDAC1 identified in a colon adenocarcinoma (COSV54738458; cancer.sanger.ac.uk/cosmic) merits further investigation given our present finding that it promotes HKI binding." (PMID 39930004, 2025). "Moreover, the expression of VDAC1 was related to the estimated infiltration value of cancer-associated fibroblasts in bladder urothelial carcinoma, colon adenocarcinoma, kidney renal papillary cell carcinoma, and testicular germ cell tumors." (PMID 35958281, 2022). "Significant alterations in voltage-dependent anion channel-1 (VDAC1, a mitochondrial protein in the outer mitochondrial membrane that causes a central pore and is considered a major protein for mitochondria-mediated apoptosis) were caused by hierridin B on colon adenocarcinoma cell line HT-29." (PMID 36286449, 2022).
depression (3 papers, 2024). "Here, we show the role of MAMs, particularly the formation of a tripartite complex involving IP3R3, GRP75, and VDAC1 within MAMs, in facilitating communication between the ER and mitochondria in microglia, thereby contributing to the development of depression-like phenotypes in male mice." (PMID 38890305, 2024).
endometrial carcinoma (3 papers, 2023 to 2024). A malignant tumor arising from the epithelium that lines the cavity of the uterine body. "MCU upregulation enhances mitochondrial activity and promotes clone formation and migration of endometrial cancer cells; it also interacts with VDAC1 to enhance regulation of mitochondrial calcium uptake and promote endometrial cancer progression." (PMID 38711526, 2024).
hypothyroidism (3 papers, 2015 to 2023). Abnormally low levels of thyroid hormone. "To assess whether hypothyroidism and T2 administration to Hypo rats might affect BAT mitochondrial density, we evaluated: mitochondrial content (expressed as mitochondrial protein/100 mg tissue), COX activity, citrate synthase, VDAC1 content and COX IV immunohistochemistry." (PMID 25658324, 2015).
liver cancer (3 papers, 2022 to 2025). An epithelial or non-epithelial malignant neoplasm that arises from the liver. "In the present study, with the addition of the calcium channel inhibitor 2-APB, OA/5FU co-treatment regulated the expressions of Grp75, PDI, and VDAC1, the Ca2+ channel-related proteins, in liver cancer cells." (PMID 40243820, 2025). "In conclusion, the upregulated lncRNA HABON under hypoxia inhibits hypoxia-induced necroptosis of liver cancer cells by interacting with VDAC1 and regulating the opening of mPTP." (PMID 35387966, 2022). "Meanwhile HABON could interact with mitochondrial outer membrane protein VDAC1, and promote the survival of liver cancer cells by inhibiting the opening of mPTP." (PMID 35387966, 2022). "To further verify whether the damage of mitochondrial function caused by knockdown of HABON under hypoxia is mediated by VDAC1, we knockdown HABON in liver cancer cells, and treated samples with mPTP inhibitor Cyclosporin A (CsA)." (PMID 35387966, 2022).
lung squamous cell carcinoma (3 papers, 2016 to 2023). "MiR-320a has been reported to be decreased in human primary squamous cell lung carcinoma, and over-expression of VDAC1 is associated with worse outcomes in a number of cancers." (PMID 27304056, 2016). "VDAC1 is overexpressed in cervical and lung squamous cell carcinoma being down-regulated in esophageal and oral squamous cell carcinoma (our results)." (PMID 37046443, 2023). "Previous studies have reported that expression of miR-320a was decreased in human primary squamous cell lung carcinoma, which prompted us to investigate whether there is a functional link between decreased miR-320a and a high expression of VDAC1." (PMID 27304056, 2016).
renal fibrosis (3 papers, 2020 to 2024). A final common manifestation of a wide variety of chronic kidney diseases characterized by glomerulosclerosis and tubulointerstitial fibrosis. "Although the role of VDAC1 in different renal diseases has been established, valuable evidence to support the claim that VDAC perturbation causes or exacerbates renal fibrosis remains to be determined." (PMID 36277193, 2022). "In this study, the expression of VDAC1 was elevated in kidney after UUO, and blockage of VDAC1 attenuated UUO-induced renal fibrosis, inflammation and cGAS-STING pathway activation." (PMID 38972937, 2024). "Collectively, these data indicate that VDAC1 oligomerization is involved in mtDNA release and activation of cGAS-STING signaling pathway in the progression of renal fibrosis." (PMID 38972937, 2024). "Mechanistically, PKC-δ activation resulted in mitochondrial membrane VDAC1 oligomerization, followed by the release of mtDNA, and subsequently activated cGAS-STING signaling pathway, and promoted inflammatory responses which contributed to the renal fibrosis." (PMID 38972937, 2024).
squamous cell carcinoma (3 papers, 2018 to 2023). A carcinoma arising from squamous epithelial cells. "The expression of VDAC1 in squamous cell carcinoma cases presents an additional problem." (PMID 37046443, 2023). "Why VDAC1 expression in squamous cell carcinoma cases did not attract much attention is difficult to tell." (PMID 37046443, 2023). "In the squamous carcinoma cell line SCC-9, ATF2 translocates to the mitochondria following genotoxic stress and disrupts the Hexokinase 1 (HK1)—Voltage dependent anion channel 1 (VDAC1) complex, thereby compromising mitochondrial membrane pore permeability and promoting apoptosis." (PMID 30497386, 2018). "However, no other VDAC1-HK interactions in cases of squamous cell carcinoma were reported to date and this topic requires some further research." (PMID 37046443, 2023).
steatosis (3 papers, 2014 to 2020). Increased lipid within the cytoplasm of cells. "The VDAC1-based peptide, thus, offers a promising therapeutic approach for steatosis and NASH." (PMID 33114780, 2020). "To demonstrate the induction of T2D, steatosis, and NASH and the effects of the VDAC1-based peptide, R-Tf-D-LP4, we first analyzed the livers for several characteristic parameters of these pathological states." (PMID 32093016, 2020). "In our previous study, we demonstrated the effectiveness of the VDAC1-based peptides, Tf-D-LP4, in treating steatosis and NASH as induced in STZ/HFD-32 fed mice." (PMID 32093016, 2020). "Recently, we demonstrated that a cell-penetrating VDAC1-based peptide, R-Tf-D-LP4, arrested steatosis and the NASH produced by feeding mice a high-fat diet (HFD-32), and reversed liver pathology to a normal-like state." (PMID 33114780, 2020). "In addition, closure of the VDAC channel produces steatosis both in alcoholic steatohepatitis and NASH because VDAC1 participates in the complex responsible for transporting fatty acids across the OMM." (PMID 33114780, 2020).
Anxiety (2 papers, 2021 to 2022). Intense feelings of nervousness, tension, or panic often arise in response to interpersonal stresses. "In the current study, we have provided in vivo evidence that partial reduction of VDAC1 mediated mitophagy, autophagy, synaptic, reduced P‐Tau pathology, and lessened memory impairment and anxiety symptoms in a murine model." (PMID 35801276, 2022).
autism (2 papers, 2015 to 2024). Persistent deficits in social interaction and communication and interaction as well as a markedly restricted repertoire of activity and interest as well as repetitive patterns of behavior. "A potential involvement of VDAC-1 is also proposed for patients with autism where antibodies against the hexokinase-1 (HK-1) have been found." (PMID 38474278, 2024).
Autoimmunity (2 papers, 2021 to 2022). The occurrence of an immune reaction against the organism's own cells or tissues. "Antibodies against VDAC1 can also be found in the serum of B-ALL children, indicating that VDAC1 triggered autoimmunity, and leaded to elevation of VDAC1 autoantibody." (PMID 35109855, 2022).
cervical (2 papers, 2016 to 2020). "Thus, VDAC1 may promote the malignant progression of HPV-related disease, and treatments designed to suppress VDAC1 could prevent the progression of HPV-induced cervical disease." (PMID 27419626, 2016).
ciliopathy (2 papers, 2020). A genetic disorder of the cellular cilia or the cilia anchoring structures, the basal bodies, or of ciliary function. "We further found that VDAC1-ΔC represses ciliogenesis and thus participates in ciliopathy, a group of genetic disorders involving dysfunctional primary cilium." (PMID 33238609, 2020). "As part of an integrated model favoring a better adaptability to hypoxia, VDAC1-ΔC appears as a new biomarker with a potential in unraveling basic mechanisms of cancer and ciliopathy development." (PMID 33238609, 2020).
Desminopathy (2 papers, 2016 to 2021). "Desmin-positive protein aggregates correlate with high levels of ATF2, voltage-dependent anion-selective channel protein 1 (VDAC1), and BCL2 Associated X (BAX) in muscle fibers of desminopathy patients." (PMID 34272480, 2021). "This pathological analysis presents the correlation between VDAC1 and desmin, and apoptosis related proteins are correlated in the desminopathy." (PMID 27941998, 2016). "The deeply mechanism of VDAC1 in the desminopathies need to be furtherly explored, so as to the mitochondrial dysfunction." (PMID 27941998, 2016). "Immunofluorescence results showed that VDAC1 was accumulated in the desmin highly stained area of muscle fibers of desminopathy patients or desminopathy rat model compared to the normal ones." (PMID 27941998, 2016). "All above, we presented powerful evidences that VDAC1 are correlated with the desminopathies." (PMID 27941998, 2016). "VDAC1 is involved in desmin aggregation in the patients with desminopathy." (PMID 27941998, 2016). "Relationships between desminopathies and Voltage-dependent anion channel 1 (VDAC1) remain unclear." (PMID 27941998, 2016). "Meanwhile apoptosis related proteins bax and ATF2 were involved in desminopathy patients and desminopathy rat model, but not bcl-2, bcl-xl or HK2.VDAC1 and desmin are closely relevant in the tissue splices of deminopathies patients and rats with desminopathy at protein lever." (PMID 27941998, 2016).
endothelial dysfunction (2 papers, 2020 to 2025). In vascular diseases, endothelial dysfunction is a systemic pathological state of the endothelium (the inner lining of blood vessels) and can be broadly defined as an imbalance between vasodilating and vasoconstricting substances produced by (or acting on) the endothelium. "Since TPPP3 could enhance the stabilization of VDAC1, the roles of VDAC1 in TPPP3-medicated endothelial dysfunction were explored in TPPP3 overexpressed HUVEC." (PMID 33082910, 2020).
germ cell tumor (2 papers, 2016 to 2022). A benign or malignant, gonadal or extragonadal neoplasm that originates from germ cells. "We chose NT2, a human germ cell tumor cell line to see whether knock down of CFTR affects the VDAC1 mediated pathway." (PMID 27483469, 2016).
infertile (2 papers, 2020 to 2025). "A significant degree of growth retardation characterizes VDAC1/3 −/− mice; and VDAC3 −/− deficient male mice show the peculiarity of infertile, with a disassembled sperm tail, the flagellum essential for sperm motility." (PMID 33036380, 2020). "While VDAC1 is mainly located in cells of reproductive organs necessary to support the development of gametes, VDAC2 and VDAC3 are expressed in a specific portion of sperm and oocyte, and genetic variants or the aberrant regulation of these genes are correlated with infertility." (PMID 33036380, 2020).
ischemia reperfusion injury (2 papers, 2020 to 2025). Adverse functional, metabolic, or structural changes in ischemic tissues resulting from the restoration of blood flow to the tissue (reperfusion), including swelling; hemorrhage; necrosis; and damage from free radicals. "In ischemia-reperfusion injury, Mff interacts with VDAC1 to regulate mitochondrial permeability transition pore opening, promoting mitochondrial fission and cellular apoptosis." (PMID 40766842, 2025). "VDAC1 is highly permeable to Ca2+, and in cardiac ischemia–reperfusion injury (IRI), VDAC1 promotes damage, while VDAC2 may have a protective role." (PMID 32664576, 2020).
lymph node metastasis (2 papers, 2016 to 2021). "By the factors analyzed, the results revealed that the expression of VDAC1 (HR = 1.544, 95%CI:0.794–3.0,P = 0.021) and lymph node metastasis (HR = 5.375, 95% CI:1.225–23.584,P = 0.026) both were independent prognostic factors." (PMID 27659305, 2016).
meningitis (2 papers, 2020 to 2025). A disorder characterized by acute inflammation of the meninges of the brain and/or spinal cord. "The identification of the interaction between RfeA and the mitochondrial protein VDAC1 as a mechanism for inducing pyroptosis and increasing BBB permeability significantly broadens our understanding of the strategies employed by bacterial virulence factors to cause meningitis." (PMID 40999536, 2025).
myeloma (2 papers, 2021 to 2023). "In human CD45+ U266 myeloma cells, VDAC1 might sensitize to many extracellular stimuli that trigger apoptosis via the mitochondrial pathway." (PMID 34579758, 2021).
osteosarcoma (2 papers, 2019 to 2023). A usually aggressive malignant bone-forming mesenchymal neoplasm, predominantly affecting adolescents and young adults. "Furthermore, DXR-resistant osteosarcoma cells also showed a reduction of mitochondrial mass, confirmed both with NAO fluorescence and the decreased expression of two mitochondrial markers, VDAC1 and TOM20." (PMID 36900165, 2023).
pituitary adenocarcinoma (2 papers, 2024 to 2025). A rare adenocarcinoma with poor prognosis, arising from the adenohypophysial cells of the anterior lobe of the pituitary gland or pre-existing adenomas. "In pituitary adenocarcinomas, reduced expression of BAX and VDAC1 genes were associated with resistance to apoptosis and thus promoted tumor development." (PMID 41614769, 2025).
polycystic ovary syndrome (2 papers, 2021 to 2025). A disorder that manifests as multiple cysts on the ovaries. "Metformin also has been reported to increase VDAC1 expression levels in NCaP cells along with increased the levels of IP3R1, IP3R2, IP3R3, and MCU mRNA, as well as VDAC1 protein, and in polycystic ovary syndrome (PCOS)-like rats treated with metformin." (PMID 34671273, 2021). "Metformin’s anti-cancer effects can be mediated through induction of VDAC1 overexpression, as shown in NCaP cells in polycystic ovary syndrome-like rats and the presence of citral in RD cells." (PMID 34671273, 2021). "In addition, metformin increased VDAC1 expression levels in NCaP cells and in polycystic ovary syndrome-like rats, and in the presence of citral." (PMID 34671273, 2021). "Additionally, metformin elevated VDAC1 expression levels in polycystic ovary syndrome-like rats." (PMID 40430574, 2025).